RN7SL617P (RNA, 7SL, cytoplasmic 617, pseudogene)
Gene: Miscellaneous RNA gene on chromosome 6 (110,439,996 to 110,440,303, reverse strand). Ensembl gene ENSG00000241162.
Homologues: Orthologues: chimpanzee Metazoa_SRP (100% identical), macaque Metazoa_SRP (80% identical), rabbit Metazoa_SRP (66% identical), rat Metazoa_SRP (66% identical). Paralogues in human: RN7SL2 (72% identical), RN7SL5P (72% identical), RN7SL1 (71% identical), RN7SL3 (71% identical), RN7SL481P (70% identical), RN7SL4P (70% identical), RN7SL33P (70% identical), RN7SL493P (69% identical), RN7SL543P (69% identical), RN7SL769P (69% identical), Metazoa_SRP (69% identical), RN7SL184P (69% identical), and 702 more.